KRAS (KRas proto-oncogene, GTPase)
Diseases named in the same sentence as KRAS in open-access papers (continued):
Sharing a sentence is not in itself a finding about the gene and the disease.
colorectal cancer (continued). "The most striking and consistent finding that we and others have found is the association between PIK3CA mutation and KRAS mutation in colorectal carcinoma, though some have not reported this finding." (PMID 23785428, 2013). "Consequently, cetuximab has been approved for reimbursement for wild-type KRAS advanced colorectal cancer patients in Canada." (PMID 22745668, 2012). "Colorectal cancer has previously been split into at least three groups based on methylation profiles: non-CIMP tumors, CIMP-high tumors associated with BRAF mutations and CIMP-low mutations associated with KRAS mutations." (PMID 23034185, 2012). "For instance, colorectal cancer patients who present mutations in KRAS or BRAF do not respond to panitumumab, a monoclonal antibody against EGFR, recently approved by FDA as a monotherapy against metastatic colorectal carcinoma." (PMID 23207070, 2012). "In this review we examine the history of KRAS, its prognostic value in patients with colorectal cancer, and evidence supporting its predictive value in determining appropriate therapies for patients with colorectal cancer." (PMID 23202889, 2012). "In lung cancer, although the frequency of KRAS mutations is similar to that in colorectal cancer, these mutations are not reported to be a predictive marker." (PMID 22994622, 2012). "Taken together, the literature on let-7 and miR-143 miRNAs in colon cancer highlights the potential that miRNA-based therapies may have in targeting KRAS-driven colorectal cancers." (PMID 23202889, 2012). "This was supported by the National Cancer Institute of Canada Clinical Trials Group and Australasian Gastro-Intestinal Trials Group CO.17 trial, which demonstrated that cetuximab offers good QOL and survival benefits for pretreated patients with advanced, wild-type KRAS colorectal cancer." (PMID 22747970, 2012). "Taken together, these results suggest PI3KCA gain-of-function mutations may predict sensitivity to PI3K pathway inhibitors, whereas KRAS and BRAF mutations may lead to resistance in some tumor types such as colorectal cancer." (PMID 22970424, 2012). "Interestingly, BRAF mutations, which are predominantly mutually exclusive of mutant KRAS, have also been associated with resistance to anti-EGFR treatment in colorectal cancer." (PMID 23202889, 2012). "It has recently been shown that receptor tyrosine kinases have control of PI-3K signaling in human KRAS mutant colorectal cancers and PI3-K may be involved in maintenance of the tumor phenotype after transformation." (PMID 22570785, 2012). "Finally, we investigated the effect of transfection with either KRAS wild-type or KRAS G12D as well as TNFalpha stimulation and Wortmannin treatment on Abi1 expression in KRAS wild-type colorectal carcinoma cells." (PMID 22808230, 2012). "Consistent with that, we could show increased Akt phosphorylation and overexpression of Abi1 upon TNFalpha stimulation in KRAS wild-type colorectal carcinoma cells." (PMID 22808230, 2012). "It has become clear that certain molecular features, such as APC-, KRAS-, or BRAF-mutations or microsatellite instability are associated with different pathways of tumorigenesis, leading to clinically and morphologically distinct colorectal carcinoma entities." (PMID 22808230, 2012). "Specific alterations of the EGFR gene, including copy number variations, and oncogenic activation of EGFR downstream effectors such as KRAS and BRAF had been previously reported as the genetic events underlying the response to cetuximab plus chemotherapy in colorectal cancer." (PMID 22152101, 2011).
colorectal cancer (continued). "Mutation in the KRAS gene is unlikely to be a resistant mechanism in this disease, as opposed to lung or colorectal cancer." (PMID 24212772, 2011). "In addition, none of the previous studies has comprehensively examined potential confounding effect of key molecular biomarkers in colorectal cancer, including the CpG island methylator phenotype (CIMP), and KRAS, BRAF and PIK3CA mutations." (PMID 21949851, 2011). "KRAS mutations only accounts for 30-40% of the non-responders to EGFR targeted MoAbs in colorectal cancer." (PMID 21439039, 2011). "Mutations in KRAS have recently become established as a negative predictive marker for the benefit of EGFR monoclonal antibodies in advanced colorectal cancer." (PMID 21811258, 2011). "Colorectal cancers lacking oncogenic alterations in genes encoding EGFR downstream effectors such as KRAS, BRAF, PIK3CA, and PTEN have the highest probability of response to anti-EGFR therapies." (PMID 22152101, 2011). "Mutations in the EGFR kinase domain predict sensitivity to the tyrosine kinase inhibitors gefitinib and erlotinib in lung adenocarcinoma, while activating point mutations in KRAS and BRAF confer resistance to the anti-EGFR monoclonal antibody cetuximab in colorectal cancer." (PMID 21943394, 2011). "Several groups have recently validated that KRAS mutations are a negative predictor of colorectal carcinoma response to monoclonal antibodies (e.g. panitumimab and cextuximab) targeting epidermal growth factor receptor (EGFR)." (PMID 21738606, 2011). "In the case of colorectal cancer, loss of APC and activation of KRAS are common." (PMID 20298593, 2010). "Colorectal cancer arises through a multistep carcinogenic process in which genetic and epigenetic alterations (e.g., microsatellite instability (MSI), CpG island methylation, mutations in KRAS, BRAF and PIK3CA) accumulate in a sequential manner." (PMID 20808308, 2010). "Two large prospective studies conducted in stage II–III colon cancer and in advanced colorectal cancer have shown that KRAS mutation is not a prognostic factor." (PMID 20842128, 2010). "Mutational analysis of the KRAS gene has recently been established as a complementary in vitro diagnostic tool for the identification of patients with colorectal cancer who will not benefit from anti-epidermal growth factor receptor (EGFR) therapies." (PMID 20385028, 2010). "In addition, mutations in KRAS, BRAF and PIK3CA are associated with a worse outcome in patients with colorectal cancer." (PMID 20098682, 2010). "Recently a number of randomized trials have shown that patients with advanced colorectal cancer do not benefit from therapies targeting the epidermal growth factor receptor when their tumors harbor mutations in the KRAS, BRAF and PIK3CA genes." (PMID 20098682, 2010). "Codon 12 mutations usually lead to KRAS activation in colorectal cancer cell lines, but the activation status was not formally tested in EGI-1." (PMID 20565817, 2010). "KRAS mutation frequency in our examinations showed 36.6% for NSCLC and 30% for colorectal cancer." (PMID 21197450, 2010). "In addition, an increasing number of tumors with either KRAS or BRAF mutation was observed with increasing age, in agreement with a recent report on young patients with colorectal cancer." (PMID 21103049, 2010). "Two human CRC cell lines, namely HCT116 and LoVo, which have an activating mutation in the KRAS gene resulting in elevated MEK/ERK activities, were thereby chosen to further analyze the regulation and role of serpinE2 expression in human colorectal cancer cells." (PMID 20942929, 2010). "In addition to inducing BRAF binding to CRAF in NRAS mutant cells, 885-A and sorafenib also induce this binding in WM1791c melanoma cells and in SW620 and HCT116 colorectal carcinoma cells, all of which express mutant KRAS." (PMID 20141835, 2010).
colorectal cancer (continued). "Our study was carried out to clarify the involvement of SMAD4 in the development and progression of colorectal carcinoma where it is reported to be mutated or deleted in about 20% of invasive cases and the relationship between the mutant status of SMAD4 and KRAS genes." (PMID 20565773, 2010). "It has become clear that patients with colorectal cancer whose tumor has an activating mutation in KRAS do not respond to monoclonal antibody therapies targeting EGFR." (PMID 19386128, 2009). "Concurrent KRAS mutations were observed in 3/136 tumors and although it remains a rare finding suggests that repeated KRAS targeting may occur during colorectal cancer progression." (PMID 19832985, 2009). "It is interesting that KRAS mutations were found in both cell lines (HuCCT1 and OZ) considered refractory to vandetanib in this study, and KRAS mutation has been reported as a mechanism of resistance to EGFR inhibitors in lung and colorectal cancers." (PMID 19319137, 2009). "Activating KRAS mutations are strong independent negative predictors of response to such treatment and mutational testing has been included in colorectal cancer practice guidelines." (PMID 19439077, 2009). "Second, KRAS and BRAF genes are mutated in approximately 50% of colorectal cancers." (PMID 19014680, 2008). "In microsatellite-unstable colorectal cancer cell lines, the effect of BRAF inhibition depended on whether the cell harboured a BRAF or a KRAS mutation." (PMID 19018267, 2008). "Therefore, we have carried out a systematic quantitative characterisation of four mutant isogenic cell lines, comparing the two most common (G12D and G12V) and two rare (G12A and G12C) oncogenic mutations found in colorectal cancer with the parental SW48 line, which is wild-type for KRAS." (PMID 41266617, 2026). "We hypothesize that combining CD47 blockade with therapies that further reduce myeloid immunosuppression, a key mediator of immunotherapy resistance in MSS colorectal cancer, such as KRAS inhibitor, STING agonist, TLR9 agonist, GM-CSF, or inflammasome modulation, could be effective." (PMID 41171165, 2025). "Class 2–mutant and class 3–mutant colorectal cancers frequently co-occurred with additional Ras pathway mutations (29.0% and 45.7%, respectively, vs. 2.40% in class 1; P < 0.001), often at atypical sites (KRAS noncodon 12/13/61, NRAS, or NF1)." (PMID 39751654, 2025). "By analogy with BRAF mutations, we wondered whether atypical KRAS mutations in colorectal cancers without BRAF mutations also tended to have concomitant mutations in Ras pathway genes." (PMID 39751654, 2025). "Previous studies have shown that colorectal cancer patients with G13D mutations benefit from first-line chemotherapy plus cetuximab, but their progression-free survival (PFS), OS, and response rates(RR) are still lower than those of patients with wild-type KRAS tumors." (PMID 40308511, 2025). "In addition, the Y chromosome gene KDM5D drives male-specific metastasis and worse outcomes in colorectal cancer harboring KRAS alterations, which activates STAT4 to increase KDM5D, repressing the expression of genes governing cell adhesion and immune recognition." (PMID 39751827, 2025). "The synergistic effect of iron oxide, glucose, and oleuropein was reflected by the increased colorectal cancer cell (SW480) apoptosis and reduced proliferation, invasion, and metastasis through inhibiting long non-coding RNA associated with the KRAS pathway and inhibiting the KRAS-influenced genes." (PMID 40284008, 2025).
colorectal cancer (continued). "Specifically, we tested whether DPP4 reconstitution enhances sensitivity to ICIs in the MC38 colorectal cancer cell line, which does not harbor KRAS mutations." (PMID 41283988, 2025). "In addition, in KRAS-mutant colorectal cancer, Slc7a5 disruption abrogates tumor cell growth." (PMID 38617535, 2024). "The potential interplay or distinct impact of mutations within the EGFR pathway (EGFR, KRAS, NRAS, BRAF, PI3KCA), along with polymorphisms in genes related to 5-fluorouracil and oxaliplatin (DPYD, TYMS, GSTP1, MTHFR, ABCB1), on the prognosis of colorectal cancer remains uncharted territory." (PMID 38248103, 2024). "This loss of KRAS G12C could be due to the sensitivity threshold of the NGS assay or, alternatively, a reversion to the wild type, which has also been described in colorectal cancer, whereby loss of this mutation is a mechanism the tumor uses to escape immune detection." (PMID 39195317, 2024). "However, evidence of acquired or de novo resistance to covalent G12C inhibitors has already been demonstrated, with only approximately 40% of patients showing partial response to KRAS-targeting monotherapies in lung adenocarcinoma and less than 20% in colorectal cancer." (PMID 39687047, 2024). "Despite the limited number of tests conducted, KRAS mutations were detected in 3.33% (n = 5) of colorectal cancer (CRC) patients, while 7.33% exhibited the non-mutated or wild-type form, leaving 89.33% (n = 135) of cases classified as unknown." (PMID 39728065, 2024). "Molecularly defined groups of colorectal cancers such as microsatellite instability (MSI)-high tumors and cancers with alterations in the receptor tyrosine kinase/KRAS/BRAF pathways, such as KRAS/NRAS or BRAF mutations and ERBB2 amplifications, may benefit from targeted therapies." (PMID 39452477, 2024). "In a study conducted in 2012, where 252 patients with colorectal cancer and 293 subjects with negative results from colonoscopy were screened, Cologuard (KRAS mutation + fecal hemoglobin + NDRG4 and BMP3 methylation) exhibited a sensitivity of 85% and specificity of 90%." (PMID 38681199, 2024). "KRAS, one of the most frequently mutated RAS isoforms in humans, is implicated in various cancers, including ~90% of pancreatic ductal adenocarcinomas (PDAC), 43% of colorectal cancers (CRC), 30–35% of non–small cell lung cancers (NSCLC), and 25–30% of lung adenocarcinomas." (PMID 38684865, 2024). "Mutations in the RAS gene family, encompassing KRAS, HRAS, and NRAS, represent a prevalent genetic alteration in colorectal carcinoma (CRC)." (PMID 38844562, 2024). "The effectiveness of EGFR (epidermal growth factor receptor) and VEGFR (vascular endothelial growth factor receptor) inhibitors faces limitations in KRAS wild-type colorectal carcinoma (CRC)." (PMID 38844562, 2024). "The existence of pathophysiological differences among the different mutant KRAS is further supported by clinical observations indicating that patients with mutant KRAS colorectal cancer may respond to targeted therapy depending on the type of point mutation they express." (PMID 37627169, 2023). "Therefore, it is important to determine whether Fn infection is a critical factor that modifies response to chemotherapy and the prognosis of colorectal cancers with MSI-H and KRAS mutations." (PMID 37772997, 2023). "The MEK and MET Inhibition in Colorectal Cancer trial (MErCuRIC1) was a phase I clinical trial aiming to test the combination of crizotinib with a MEK inhibitor, either binimetinib or PD-0325901, in CRC patients with either a KRAS mutation or aberrant c-MET activation." (PMID 37569406, 2023).
colorectal cancer (continued). "Mn was significantly negatively correlated with the KRAS mutations, and Rb was noticeably negatively correlated with the MSI status, indicating certain TEs might contribute to the pathogenesis of molecular subtype-specific colorectal cancer." (PMID 37325050, 2023). "Although several studies demonstrated that MSI-H, BRAF mutation, MLH1 hypermethylation, or CIMP-high, characteristics shared with CMS1 colorectal cancer were associated with high levels of Fn infection, none of these studies showed any association between Fn infection and KRAS mutations." (PMID 37772997, 2023). "However, these inhibitors have several limitations, including their ineffectiveness in combating colorectal cancer and their lack of efficacy against other KRAS mutations." (PMID 37504287, 2023). "Colorectal cancer with KRAS mutations is a negative marker for anti-EGFR targeted drugs." (PMID 37311935, 2023). "In this study, we aimed to determine whether and how KRAS mutations are associated with Fn infection compared with the association of BRAF mutation, MLH1 hypermethylation and MSI-H with Fn using a previously characterized colorectal cancer cohort." (PMID 37772997, 2023). "In addition, statins abrogated K-Ras membrane localization in KRAS-mutated colorectal cancer cells but not in L-OHP." (PMID 37069612, 2023). "However, in colorectal cancer, ML algorithms can distinguish between KRAS mutated and non-KRAS mutated samples using tumor microbiome." (PMID 37573394, 2023). "Thus, the investigators conclude that PCSK9 inhibition may be a valid adjuvant therapy for APC/KRAS mutant colorectal cancer by suppression of the KRAS/MEK/ERK oncogenic pathway." (PMID 36900189, 2023). "Thus, even in KRAS mutant colorectal cancer, CERS4 expression may be reduced due to the influence of the NF-kB pathway." (PMID 37758931, 2023). "Moreover, a low protein expression of MATE1 was found in KRAS-driven colorectal carcinoma." (PMID 36839686, 2023). "Moreover, the KRAS G12D-TCR-T cells may be further tried to treat cancer patients who carry KRAS G12D mutation, such as NSCLC and colorectal cancer." (PMID 35725570, 2022). "Only 3 studies of the colorectal cancer patients in our analysis had a KRAS codon 61 mutations which is not surprising given that the majority of KRAS mutations reported in human tumours are in codon 12, with mutations in codons 13 and 61 accounting for only 1.7-9 percent." (PMID 35782059, 2022). "In addition to lung and colorectal cancer, oncogenic KRAS could also facilitate HIF-1α activation and promote pancreatic tumor growth under hypoxic conditions." (PMID 36550998, 2022). "Additionally, we compared and contrasted SAMHD1 expression according to KRAS mutation status, BRAF mutation status, tumor location, and defective DNA mismatch repair status, as they were frequently mutated genes or risk parameters in colorectal cancer." (PMID 35978833, 2022). "However, clinical studies have unexpectedly reported that the response rate to these drugs is high in patients with non-small cell lung cancer (NSCLC) but limited in patients with colorectal cancer 10-12, suggesting the intertumor heterogeneity in KRAS-mutant cancers." (PMID 35836817, 2022).